IL4 (interleukin 4)
Diseases named in the same sentence as IL4 in open-access papers (continued):
Sharing a sentence is not in itself a finding about the gene and the disease.
infection (continued). "In accordance with the elevated numbers of neutrophils and eosinophils in the peripheral blood and histological sections, we detected prominent increases in TH2 cytokines, such as IL-4, IL-5, IL-13 and IL-33, during the acute phase of infection, particularly from the 3rd day p.i. onward." (PMID 26135397, 2015). "CD4+ T cell-derived IL-10 is produced by IL-4+ Th2 cells in the early phase of infection." (PMID 26195548, 2015). "Instead, only CD4+ Foxp3− IL-4+ Th2 cells showed increased IL-10 production upon infection." (PMID 26195548, 2015). "Together, these results indicate that infection, IFNγ and TNFα have negative effects on mitochondrial respiration, which is alleviated by IL-4, while IL-6 afforded some protection, but only against loss of complex-IV." (PMID 26481427, 2015). "In microenvironments dominated by IL-4 or IL-13, macrophages undergo M2 polarization (also known as alternative activation), which mediates tissue repair and immune escape of pathogens and tumors, leading to persistent infection and tumor development." (PMID 26091535, 2015). "IL-4, overexpressed only during the infection clearance phase, partially abrogates the mitochondrial dysfunction by reducing enhanced NO production, signifying the beneficial role IL-4 might play during infection clearance." (PMID 26481427, 2015). "IL-4-producing Th2 cells predominate in the early phase of infection." (PMID 26195548, 2015). "We speculated that T. spiralis might induce the recruitment of IL-4 secreting eosinophils to sites of infection as a mechanism to prevent destruction of NBL by autophagy." (PMID 26720604, 2015). "Additionally, exposure of a human airway epithelial cell line (A549) to IFNγ for 48 h prior to RSV infection reduced 2-day post-infection viral titers when compared to IL-4 treated or control cells." (PMID 26438053, 2015). "Intracellular staining of CD4+ T lymphocytes revealed that mice reconstituted with CD4+Foxp3- T cells and CD4+Foxp3- T cells + Treg showed augmented production of IFN-γ, IL-17 and IL-4, at weeks 2 and 6 post-infection, when compared with mice receiving Treg cells only." (PMID 26512987, 2015). "However, IL-17 and IL-4, showed a significant decreased level during the infection, especially after 2 days post infection." (PMID 24666970, 2014). "Infection of RBLs with EBV results in activation to lymphoblasts that are phenotypically similar to those generated by physiological stimulation with CD40L plus IL-4." (PMID 24097438, 2014). "This consequently elevated production of the Th2 cytokine, IL-4 and IL-13, may explain why these mice displayed reduced dendritic cell maturation and naïve T cells priming following infection." (PMID 24801628, 2014). "In addition, IL-4, a cytokine related to Th2 responses, was increased only in the liver of WT mice post infection." (PMID 25119429, 2014). "A careful analysis of the systemic (serum) cytokine levels in mice chronically infected with the Omani isolate revealed that type 1 (IFN-γ, TNF-α, GM-CSF), type 2 (IL-5, IL-13, to a lesser degree IL-4), and type 17 (IL-17) cytokines coexisted throughout the infection." (PMID 25398130, 2014). "IL-4-mediated modulation of DC function was also found in other infection models." (PMID 25126585, 2014). "IL-4 is recognized as one of the most critical cytokines for mediating protective immunity to H. polygyrus; however, Ab-mediated depletion of IL-17A has recently been found to have little effect on the outcome of primary infection with this parasite." (PMID 25114104, 2014). "We also performed individual qRT-PCR analysis of the top upregulated and downregulated miRNAs at 24 h and 7 days post-infection of samples generated with wild-type EBV, EBNA-2- and LMP-1-deficient viral particles and samples generated through IL-4/CD40L activation." (PMID 25200074, 2014).
infection (continued). "Although macrophage accumulation in both IL-4C and infection models is the direct result of IL-4 driven proliferation, anti-apoptotic properties of IL-4 may also make a significant contribution to the final numbers." (PMID 25319331, 2014). "This was further confirmed in a study by King and Mohrs that demonstrated that in a Th2 setting induced by infection with H. polygyrus, the majority of IL-4 producing CD4+ T cells in the reactive lymph nodes co-express canonical TFH cells markers and localised within the B cell follicles." (PMID 24516382, 2014). "Our initial data point to the Th cell compartment as the main cellular source of IL-4 and IL-13 early in the infection as revealed by analysis of IL-4 and IL-13 mRNA expression in the enriched pulmonary CD4+ population of WT mice (our own unpublished observation)." (PMID 24475277, 2014). "However, at day 3 post-infection, the Socs4R108X/R108X mice showed significantly higher levels of cytokines and chemokines, such as IL-1β, IL-4, IL-5, IL-6, IL-12p40, IL-13, IFN-γ, and KC (CXCL1), MIP-2 (CXCL2) and MCP-1 (CCL2), respectively." (PMID 24809749, 2014). "In this study, we investigated the outcome of a primary H. polygyrus infection in mice deficient in MyD88 signaling, and found that they were more resistant to infection than wild-type C57BL/6 mice and had a higher frequency of IL-4–producing CD4+ T cells following infection." (PMID 25114104, 2014). "However, studies in mice have demonstrated altered cytokine profiles over the course of infection, starting with a pro-inflammatory Th1 response, and switching to a Th0 balance (equal amounts of IL-2 and IL-4 production) during chronic infection." (PMID 24918450, 2014). "Next, we investigated whether there were changes in the cytokine milieu at the site of infection using the thoracic cavity lavage and assessed the levels of several cytokines: IL-4, IL-5, IL-13, IL-25, IL-33, and IFNγ." (PMID 24663956, 2014). "Infection of mice with Nippostrongylus brasiliensis triggers a host protective immune response characterised by increased production of Th2 cytokines IL-13 and IL-4, goblet cell hyperplasia eosinophilia and elevated levels of serum IgG1 and IgE." (PMID 24516382, 2014). "The IFN-γ and IL-4 cytokines production in the supernatants of spleen cells of experimental groups was evaluated after the final booster injection and seven weeks after the challenge infection with L. major." (PMID 25147675, 2014). "A high IL-4 response coinciding with enhanced IgG1 correlated with a failure of protection in alum + LAg immunized mice, whereas exacerbation of infection in saponin + LAg immunized mice may involve the unbalanced secretion of IL-4 in conjunction with IL-10." (PMID 24428931, 2014). "In addition, infection in all heifers was also accompanied by early IFN-γ/IL-4 cytokine production under specific PBMC stimulation, a specific IgG response and an upregulation of cytokine mRNA levels in maternal placenta." (PMID 24479988, 2014). "Splenocytes from ST2 deficient mice had no impaired production of IL-4, IL-5, IL-10 or IFNγ following ConA stimulation and this was throughout infection." (PMID 24663956, 2014). "There was a peak of cytokines IL-10, IL-13, IL-6 and IL-4, 17 weeks after infection." (PMID 24886277, 2014). "The splenocytes of vaccinated hamsters receiving liposomal rCPC and cocktail of three liposomal CPs showed higher IFN-γ, IL-2, TNF-α and IL-12 mRNA expression than all other groups but appreciable downregulation of macrophage deactivating cytokines like IL-4, IL-10 mRNAs, before and after infection." (PMID 25144181, 2014). "In the spleen, only IL-4 mRNA showed increased expression with infection." (PMID 23533629, 2013). "There was little change in IL-12 or IL-4 mRNA levels during infection." (PMID 24204622, 2013).
infection (continued). "IL-4 appear relatively late after infection, which perhaps prevents the host from succumbing to early Th1-polarized hyperactive immune response that can be detrimental to the host, and high level of IL-4 was known to antagonize the production of IFN-γ." (PMID 24148219, 2013). "IL-4 and IL-13 induce a predictable pattern of gene expression in macrophages, regardless of the associated infection or disease." (PMID 23637937, 2013). "Amongst the gene knockout mice examined only BALB/c IL-4 −/− mice developed greater numbers of IFN-γ expressing KdA5275–83 or KdF226–34 specific-CD8+ T cells compared to BALB/c WT control mice following VV-WR infection." (PMID 23383283, 2013). "In the present study, the role played by MCs in neutrophil recruitment in analyzed tissues may be attributed to the consequence of a reduction in the expressions of IL-4 or IL-10 at the site of the infection in infected mice with C48/80 treatment." (PMID 24146978, 2013). "Monitoring the sequential changes in the expression of cytokines following the infection showed that IL-33 expression peaked at day 6 PI, followed by the peak IL-4/IL-13 expression, suggesting that IL-33 plays a role in the initiation/amplification of the type 2-mediated immune response." (PMID 23536877, 2013). "In contrast to CD40L/IL4 B blasts, which usually have finite proliferative lifespans, experimental infection of resting B cells with Epstein-Barr virus (EBV) in culture regularly results in the establishment of lymphoblastoid cell lines (LCL) with indefinite proliferation potential." (PMID 23724103, 2013). "Our previous studies in mice infected with Leishmania major revealed that early in infection, the infected dermis contained an IL-4-dominant immune infiltrate that was in contrast to the generation of a mixed IL-4 and IFNγ anti-Leishmania response in the draining lymph node." (PMID 23991011, 2013). "Infection of normal resting B cells with EBV results in activation to lymphoblasts that are phenotypically similar to those generated by physiological stimulation with CD40L plus IL-4." (PMID 23724103, 2013). "While IL-4 is the main inducer of Th2 responses, paradoxically, it has been shown that exogenously administered IL-4 can promote dendritic cell (DC) IL-12 production and enhance Th1 development if given early during infection." (PMID 24204259, 2013). "We observed that STAg-pretreated IL-4-/- mice efficiently controlled the infection." (PMID 24086456, 2013). "LysMcreIL-4Rα-/lox mice which lack IL-4/IL-13 induced alternative activation of macrophages were found to have increased resistance to infection, while neutralization of endogenous arginase 1 with N-hydroxy-nor-L-arginine leads to complete healing in BALB/c mice." (PMID 24204259, 2013). "IL-4 can induce the activation of STAT1, STAT3, STAT5 and STAT6 on naïve and activated CD8+ T cells in vitro, but our infections studies with VV-HA-IL-4 indicated that STAT6 was indispensible for IL-4 mediated up-regulation of cell surface IL-4Rα expression on naïve and effector CD8+ T cells." (PMID 23383283, 2013). "Additionally in the draining skin-LN there was an increase in IFN-γ and IL-4 following infection, suggesting a mixed type-1 and -2 response." (PMID 24086786, 2013). "Next we investigated whether IL-4Rα levels on CD8+ T cells were fixed/unchanged, or responsive to IL-4 during infection." (PMID 23383283, 2013). "Indeed, the bulk of our knowledge of HIV-1 trans infection is based on MDDC derived from peripheral blood monocytes by in vitro culture with IL-4 and GM-CSF." (PMID 24278768, 2013). "Only IL-1β, IL-6, TNF and IL-4 were significantly induced by infection in the spleen (the latter also in the liver), while the production of IL-12p70 and IL-13 decreased with infection, in the liver." (PMID 23459556, 2013).
infection (continued). "Impaired lamina propria Foxp3+ Treg-cell responses were associated with increased production of IL-4 and IL-13 by CD4+ T cells, demonstrating that ICOS dominantly downregulates Type 2 responses at the infection site, sharply contrasting with its Type 2-promoting effects within lymphoid tissue." (PMID 23319295, 2013). "Indeed, when Foxp3+ T cells are removed at early stages of an infection with H. polygyrus, pathology of the small intestine is significantly worse, with higher numbers of effector T cells, IL-4, and IL-13." (PMID 23053394, 2012). "Knockout perturbation analysis confirmed that IL4 produced by eosinophils was responsible for this occasional bacterial persistence, since the deletion of this node led to the complete clearance of the infection in all the simulations." (PMID 22253585, 2012). "Repeated infections with T. regenti evoke dominant production of Th2-type cytokines, and the first and most abundant cytokine detected in supernatants of skin biopsies from mice after repeated infections is IL-6, which can initiate Th2-type polarization via induction of IL-4." (PMID 23125918, 2012). "When compared with plasma samples from an independent cohort of healthy individuals, cytokines IP-10, VEGF and PDGF-BB were found to be elevated >20 times over controls during the febrile phase of infection, while IL-4, IL-9, IL-10 and IL-1ra were elevated by 10–20 times over controls." (PMID 23209847, 2012). "Similarly, it has been suggested that induction of IL-4 following LVS infection of macrophages exacerbates disease." (PMID 22428026, 2012). "Two cytokines that play a major role in the resistance to infection are IL-4 and IL-13." (PMID 23053395, 2012). "Sera IL-4 levels were significantly higher in the pAg85A-sHA2 group or the pHA vaccinated group compared to those in the psHA2 group (P < 0.05) on Day 12 after infection with the PR8 virus." (PMID 23223215, 2012). "In addition, the level of IL-4 was very low pre-infection and 2w post infection; IL-4 was also expressed at a lower level at 4w but had increased at 7w post challenge with schistosomes." (PMID 22414188, 2012). "In BALB/c mice an IL-4-driven Th2 response predominates, leading to uncontrolled infection." (PMID 23028548, 2012). "Moreover, vaccinated mice produced large amounts of IFN-γ, IL-17 and NO at 7 weeks post-infection (pi), and they showed lower arginase activity at the site of infection, lower IL-4 production and a weaker humoral immune response than infected control mice." (PMID 22876751, 2012). "However, NFATp−/− mice showed a marked increase in IL-4 mRNA in the lungs at 10 weeks post-MTb infection." (PMID 22844476, 2012). "Mice lacking either IL-4 or IL-13 are susceptible to infection with a high dose of T. muris which is expelled by wild-type animals." (PMID 23053395, 2012). "Although signaling via IL-4Rα plays a significant role in the outcome of infection with L. mexicana as well as L. major the cell targets for IL-4/IL-13 activity and whether they promote or inhibit the disease process differ significantly between species." (PMID 21245915, 2011). "In studies of infection by Fasciola hepatica and S. mansoni, the secreted antioxidant, peroxiredoxin (Prx), was shown to induce Ym1-expressing AAMs, which enhanced the secretion of IL-4, IL-5 and IL-13 from naïve CD4+T cells." (PMID 21246055, 2011). "The mice were then treated with anti-IL-4 mAb twice a week for seven weeks after infection." (PMID 21390155, 2011). "However, survival to the chronic stage of infection, representative of human disease, is dependent on modulation of the Th2 granulomatous response in order to subvert IL-4/IL-13-driven morbidity." (PMID 21858239, 2011). "Still, despite its key role in the regulation of parasite infections and resulting evolutionary significance of IL4 polymorphisms, empirical evidence of the importance of IL4 on the intensity of parasite infections in natural population is lacking." (PMID 21501512, 2011).
infection (continued). "Seven weeks post-infection, we observed approximately 20-fold increase in IL-4 mRNA expression in mice inoculated with the resistant isolate compared to that in mice inoculated with the susceptible isolate (419.9±76.33 and 16.23±5.164, respectively; p = 0.0019)." (PMID 21390155, 2011). "Seven weeks after experimental infection, however, lesions in animals treated only with normal IgG increased in thickness while those in animals treated with anti-IL-4 mAb began to decrease significantly in thickness (0.8233±0.151 and 0.35±0.02, respectively; p = 0.036)." (PMID 21390155, 2011). "However, we found that in both SHIV162p3 and SIVmac251 infected macaques, both Th-1 (IL-2, IFN-γ) and Th-2 (IL-4, IL-5, IL-6, IL-10, and IL-13) type cytokines were markedly elevated after infection." (PMID 21464951, 2011). "However, infection by the protozoan pathogens T. cruzi and L. mexicana elicited responses most similar to alternative activation by the Th2 cytokine IL-4 and to macrophage deactivation by the cytokine IL-10." (PMID 20361029, 2010). "Thus, IL-4 induces a Th1 response earlier in infection, most likely via increasing IL-12 secretion from DCs in a defined early time frame." (PMID 20442861, 2010). "Interestingly, CFA and collagen given at 7 weeks of infection at which IL-4 production was high prohibited the IL-4 production from being decreased when infection entered 15 week period." (PMID 20537152, 2010). "However, at 24 h post infection the level of IL-4 transcript was reduced with vEye3 compared to parental HSV-IL-4 (24 h)." (PMID 21139679, 2010). "Infection of macrophages with IL-4 expressing virus down-regulated IL-12 production by macrophages." (PMID 21139679, 2010). "Thus, neutralization of endogenous IL-4 in infected footpads at the time of infection resulted in a clear Th2 switch." (PMID 20442861, 2010). "In addition, the effects of PCA-5 on infection status were modified by PCA2 (IL-4, IL-5, CAP IgM and IgG2)." (PMID 21039611, 2010). "However, the Th1 response characterized by the production of IFNγ peaked early at 15 days post-infection and decreased thereafter whereas IL-4 was expressed for longer (43 days post infection)." (PMID 20356390, 2010). "Alternative activation of macrophages is induced by IL-4 and IL-13, cytokines that are produced in a Th-2 type response, particularly during allergic, cellular and humoral responses to parasitic and selected pathogen infections." (PMID 20380696, 2010). "Infection with T. canis induced elevated levels of IL-4, IL-5, and IL-10 compared to control mice." (PMID 20544012, 2010). "However, immunosuppressive cytokines such as IL-10, IL-4 and IL-13 (anti-inflammatory effect) are significantly elevated in the later stage of the infection." (PMID 20169057, 2010). "However, it is noteworthy that a significantly (P < .05) lower number of GBS were recovered in the bloodstream of IL-4−/− mice in comparison to controls, as soon as two days after infection." (PMID 19606256, 2009). "In contrast, MLN cells from Se-deficient mice secreted significantly lower level of IL-4 (P<0.01) at day 7 of infection and the level did not increase further in those isolated at day 14 of infection." (PMID 19247447, 2009). "Moreover, acute infection with the Dm28c clone of the parasite led to IL-4 deprivation and caspase-9 activation, promoting MLN atrophy with T cell depletion." (PMID 19582140, 2009). "Finally, as already assessed in the kidneys and in the blood, bacterial burden in the joints of IL-4−/− mice was significantly lower than in controls, as soon as 2 days after infection." (PMID 19606256, 2009). "All of these data indicate IL-4 produced early during an infection by innate immune cells may prime immature DC to switch to immunity or enhance maturation induced by weak stimuli." (PMID 19680551, 2009).